NUBP1 (NUBP iron-sulfur cluster assembly factor 1, cytosolic)
Description:
Component of the cytosolic iron-sulfur (Fe/S) protein assembly (CIA) machinery. Required for maturation of extramitochondrial Fe-S proteins. The NUBP1-NUBP2 heterotetramer forms a Fe-S scaffold complex, mediating the de novo assembly of an Fe-S cluster and its transfer to target apoproteins. Implicated in the regulation of centrosome duplication (By similarity). Negatively regulates cilium formation and structure (By similarity).
Synonyms: NBP; NBP1; NBP35; CIAO5
Tractability: PROTAC: ubiquitination databases record sites on it; its protein half-life has been measured.
Gene: Protein-coding gene on chromosome 16 (10,743,786 to 10,769,353, forward strand). Ensembl gene ENSG00000103274.
Subcellular location: Cytoplasm; Nucleus; Cell projection; Cytoplasm, cytoskeleton, cilium axoneme; Cytoplasm, cytoskeleton, cilium basal body; Cytoplasm, cytoskeleton, microtubule organizing center; Cytoplasm, cytoskeleton, microtubule organizing center, centrosome, centriole; Cytoplasm, cytoskeleton, microtubule organizing center, centrosome
Subcellular location (Human Protein Atlas): Cytosol; End piece; Mid piece; Principal piece; Centrosome; Golgi apparatus
Pathways (Reactome):
Metabolism: Cytosolic iron-sulfur cluster assembly
Gene Ontology:
Molecular function: 4 iron, 4 sulfur cluster binding; iron-sulfur cluster binding; molecular adaptor activity; protein binding; nucleotide binding; ATP binding; ATP-dependent FeS chaperone activity
Biological process: intracellular iron ion homeostasis; iron-sulfur cluster assembly; regulation of cell growth
Cellular component: cytoplasm; cytosol; iron-sulfur cluster assembly complex; nucleus; axoneme; centriole; centrosome; microtubule organizing center
Genetic constraint (gnomAD): Loss-of-function variants: 46 observed, 39.26 expected, observed/expected ratio (o/e) 1.17, 90% interval 0.92 to 1.5. The upper end of that interval is the gene's LOEUF score, 1.5, which puts it in group 6 of 6, group 1 being the genes least tolerant of losing a copy. Missense variants: 493 observed, 423.51 expected, observed/expected ratio (o/e) 1.16, 90% interval 1.08 to 1.25. Synonymous variants: 189 observed, 159.78 expected, observed/expected ratio (o/e) 1.18, 90% interval 1.05 to 1.34.
Homologues: Orthologues: chimpanzee NUBP1 (99% identical), macaque NUBP1 (98% identical), guinea pig NUBP1 (91% identical), dog NUBP1 (91% identical), mouse Nubp1 (89% identical), rabbit NUBP1 (88% identical), pig NUBP1 (88% identical), rat Nubp1 (88% identical), tropical clawed frog nubp1 (80% identical), zebrafish nubp1 (75% identical), Drosophila melanogaster Nubp1 (53% identical), Caenorhabditis elegans nubp-1 (52% identical). Paralogues in human: NUBP2 (42% identical), NUBPL (38% identical).
Diseases named in the same sentence as NUBP1 in open-access papers:
NUBP1 is named in the same sentence as 8 diseases in open-access papers, as found by Europe PMC text mining. Sharing a sentence is not in itself a finding about the gene and the disease. The quoted sentences say what the papers report.
colorectal cancer (1 paper, 2021). A primary or metastatic malignant neoplasm that affects the colon or rectum. "Similarly, AURKA, BAG3, NUBP1, and ANLN are all found to be dysregulated in colorectal cancer and involved in cancer progression and invasion." (PMID 34790220, 2021).
sarcopenia (1 paper, 2025). Progressive decline in muscle mass due to aging which results in decreased functional capacity of muscles. "From a clinical perspective, the potential of ENSA, FAM43A, MDH2, NUBP1, SAMM50, and TM2D1 as biomarkers is promising, as they may be measurable in peripheral blood or muscle biopsy specimens to support early screening and individualized diagnosis of AS patients at risk of sarcopenia." (PMID 41204493, 2025).
tumor (2 papers, 2021 to 2022). "We tested 24 tumor samples for BRCA1 and BRCA2 mRNA levels, normalized to the reference genes GUSB, POLR1E, and NUBP1." (PMID 35203410, 2022).
infection (1 paper, 2021). The state of being infected such as from the introduction of a foreign agent such as serum, vaccine, antigenic substance or organism. "In the meantime, the host–pathogen interaction proteome offered insight into the major proteins involved in immunity of C. curvignathus (Nubp1, Cyp6a13, GTP1-1p, and POLD1) and M. anisopliae pathogenesis (Sec8, Hsp78, Catp, Lias, and RNAh) throughout the infection process." (PMID 33806225, 2021).
NUBP1 also shares sentences with these, for which no sentence is quoted: cancer (1 paper); gastric cancer (1); liver cancer (1); sarcoma (1).